NES (nestin)
Diseases named in the same sentence as NES in open-access papers (continued):
Sharing a sentence is not in itself a finding about the gene and the disease.
tumor (continued). "Nestin positivity was detected in 65% of the RCC cases where it appeared as brown cytoplasmic staining in the endothelial cells of small newly formed capillaries and few scattered tumor cells." (PMID 39687450, 2024). "Further subgroup analyses showed that the relationship between higher tumor expression of nestin and poor OS was consistent in Asian and non-Asian studies, and in univariate and multivariate studies." (PMID 37485559, 2023). "Interestingly, we also found a marked and dense nestin-positive peritumoral astrocytic cell population, concentrated along the tumor bed of challenged GL261 tumor in pre-vaccinated mice (pre-vaccinated, tum WT, black arrowheads)." (PMID 36993983, 2023). "CSCs in these tumours were somewhat different, the markers of which were PLP, Nestin, P75, GAP43, and Sox10, with GFAP, S100, and GAP43 (as a Schwann cell marker) in differentiated cells, in neurofibroma and MPNST; and Oct4, SOX2, Nanog, MYC, KLF4, CD133, CD44, and CXCR4 in CSCs of schwannoma." (PMID 37370764, 2023). "To determine whether CAF enrichment in tumor-bearing SVZ was related to GSC enrichment in this area, we performed qPCR on biopsies of SVZ-containing GBM versus tumor core and found unchanged expression of GSC markers nestin or CD44 (P = 0.1)." (PMID 36856115, 2023). "We evaluated the stem cell signature in these patient-derived organoids and found significantly varying levels of stemness, especially in levels of CD44, nestin, and CD133 in our representative example patient tumor after receiving chemotherapy and radiation treatment." (PMID 37444398, 2023). "In their study, overexpression of Lin28b alone was not sufficient for tumor formation in Math1‐positive cerebellar granular neuron precursors or Nestin‐positive neuronal precursor cells." (PMID 37341142, 2023). "This latter consideration may indicate a process of tumor vessel formation in the PBZ, since Nestin is an endothelial progenitor marker, while Factor VIII is related to mature capillaries." (PMID 36300592, 2023). "Dusart and colleagues demonstrated, that nestin is constitutively expressed in human endothelial cells; its expression does not depend on cell proliferative status and is not specific to tumor endothelium." (PMID 35453578, 2022). "Further characterisation by matched single cell RNA-sequencing of the same tumours revealed that BCL-xL and MCL-1 expression correlated with expression of neural stem cell markers NES, SOX2 and SOX9 and the degree of malignancy within the tumours (CNA gain chromosome 7), independently of cell cycle." (PMID 35473984, 2022). "Moreover, targetable signalling events observed in in vitro models of HNSCC were also connected with downregulation of Oct4, Sox2, nestin, and CD44 expression, as well as inhibited tumour sphere formation." (PMID 35276890, 2022). "Moreover, the tumor specimens were all stained by immunohistochemistry to show the expression of DGCR8, SPI1, TNF-α, nestin, and Ki-67." (PMID 35945192, 2022). "Tumor cells at the outer part of the “pseudo-papillary” structure were CA9-positive (CA9+)/HIF-1α+, whereas cells at the inner part of this structure were CA9−/HIF-1α+ and nestin+/FOXM1+." (PMID 35785200, 2022). "Our own result proved that CD105+Nestin+ cells exist outside of the GBM margin and might be related with tumor recurrence." (PMID 36038950, 2022). "Similarly, a nestin-targeted oncolytic HSV also killed neuroblastoma tumor-initiating cells and prevented tumor formation in xenograft-bearing mice." (PMID 35493490, 2022). "Progenitor cells positive for Nestin in the cerebellum displayed more effective tumor cell transformation and severe genomic instability compared with cells that were negative for Nestin." (PMID 34772403, 2021). "Finally, nestin depletion increased E-cadherin expression while inhibiting vimentin, suggesting that nestin modulates epithelial–mesenchymal transition (EMT) to promote cell invasion, resulting in tumor metastasis." (PMID 34943921, 2021).
tumor (continued). "However, other studies have found that signaling from the tumor increases SVZ proliferation, resulting in hypertrophic, hypercellular areas and increased levels of stem cell markers such as Nestin." (PMID 34268110, 2021). "Then, IHC, RT-qPCR and western blotting were used to detect CD133, CD9 and Nestin in the absence or presence of HBO in the tumour tissues of mice following intracranial transplantation, and the results showed weak expression of CD133, CD9 and Nestin after HBO treatment." (PMID 33986256, 2021). "Additionally, correlations between Tregs and CTLs infiltration and the expression of tumor PD-L1 and various well-established CSCs markers (i.e. NANOG, SOX2, OCT4, Nestin and PDPN) are also assessed." (PMID 34201050, 2021). "Notably, high levels of CD44, CD133, Nestin and MYC protein were detectable in adherently grown CSC populations from all tumor types as well as in spheres derived from ECSC_b and GSC_c." (PMID 33800955, 2021). "Furthermore, increases in the properties of stem cells were measured by assessing the capacity for tumor formation and performing transcriptional analysis of the OSKM genes (OCT4, SOX2, KLF4 and MYC), NANOG, NES and PROM1." (PMID 34364391, 2021). "Vimentin, nestin, which are present in radial glia were also expressed in tumours, whereas neuronal marker NeuN was consistently absent." (PMID 32404936, 2020). "Immunohistochemically, CD133, CD44, and nestin expression was positive in tumor cells regardless of cell size in GC-GBM, and there was no site-dependent propensity in MS-GBM." (PMID 31655917, 2020). "Importantly, expression of the stemness marker Nestin was decreased and expression of the differentiation marker GFAP was increased in tumor tissues formed from ARS2- or MAGL-knockdown GSCs." (PMID 32532977, 2020). "In our LATS1/2 cKO mouse model, although some of the tumour markers were highly present in the centre of the tumour mass, e.g., ANKRD1, Vimentin, CK18, nestin and Ki67, some were localised towards the edges of the tumour, e.g., HOPX, AMOTL2, AXL and microglial marker C3." (PMID 32404936, 2020). "Immunohistological studies using the cell proliferation marker ki67 and stem cell/tumour cell markers, Nestin and Pax6, showed that these were present in the tumour, but not in the accompanying cortical region." (PMID 33215086, 2020). "There was a small decrease in the expression of CD271 and Nestin in the #5 GM2/GD2-positive cell line, but this alone is unlikely to be the cause of enhanced tumor growth." (PMID 31988291, 2020). "Additionally, in the tumor tissues generated by co-injection the number of dedifferentiated cells expressing OCT4, GFP, and Nestin was increased, whereas the number of cells expressing the differentiated astrocyte marker GFAP was decreased." (PMID 30804471, 2019). "Thus, similar patterns of Nestin and APELA co-expression were found at the mRNA level (RNA-ISH) and protein level (IHC) in GBM patient tumor specimens." (PMID 30917521, 2019). "It was therefore not possible to evaluate FOXA1 and Nestin expression in the primary tumor at this time." (PMID 30819139, 2019). "Moreover, Nestin knockdown increased the sensitivity of NSCLC cells to 17-AAG, while Nestin overexpression increased the viability of 17-AAG-treated tumor cells." (PMID 31695040, 2019). "After 3 days in culture, both nestin positive and negative tumor cells had invaded the hydrogel using single cell and collective cell migration modes, an observation that was even more pronounced after 7 days." (PMID 31227783, 2019). "The recruitment of F4/80+ cells was either unchanged in U87MG tumors or slightly increased in the LN229 tumor, but the increase in recruitment of Ly6G+ cells was significantly correlated with accumulation of Nestin+ and CD133+ cells observed in the co-injection tumor models of U87MG and LN229 cells." (PMID 30804471, 2019).
tumor (continued). "In BCCs of this analysis, Nestin was weakly expressed in the majority of BCCs but the tumour stroma was not separately analysed." (PMID 31065284, 2019). "Furthermore, using IHC, we found a significant overlap in cells that express both Nestin and APELA in GBM tumor tissue." (PMID 30917521, 2019). "In particular, the expression of nestin and CD105 in the vessel wall was analyzed and the micro-vessel density (MVD) was determined at a distance <1 cm and between 1 and 3.5 cm from the macroscopic tumor border." (PMID 30987226, 2019). "Additionally, the GBM stemness was impaired, and complemented with enhanced differentiation, evidenced by the low-level of Nestin and high number of GFAP-expressing cells across the tumor (p < 0.05 and p < 0.01)." (PMID 31380279, 2019). "TrkAIII transfectants also exhibit elevated expression of the NB tumour stem cell-markers CD117, SOX2, Nestin and Nanog, indicating that TrkAIII not only blocks NGF/TrkA-induced NB cell differentiation but also promotes a more NB tumour stem cell-like phenotype." (PMID 29914559, 2018). "Nestin, which is often expressed in combination with SOX and other stem cell markers, was shown to be expressed on the initiating cells of different tumor types, and was supposed to be a marker for stem cell features such as their self-renewal capacity and tumorigenicity." (PMID 30200299, 2018). "Taken together, these data show that nestin is a marker of EC in both normal and tumour tissues (with the exception of GBM), and thus is not specifically expressed by tumour-associated EC." (PMID 30279450, 2018). "The resected tumor was positive for GFAP, Ki67, vimentin, CD56, and nestin." (PMID 30583471, 2018). "At this stage, immunostaining with an antibody for human nestin allowed to detect scattered, isolated tumor cells in the normal brain parenchyma." (PMID 30242200, 2018). "In ninety-six studied GBs, 50% showed high expression level of NG2/CSPG4 in tumor cells and vessels, together with Nestin and Vimentin, but not with CD133." (PMID 30213051, 2018). "In this work we have demonstrated, for the first time, that FVIII positive tumor vessels are formed also by CD133, nestin and pStat3 positive cells, suggesting that in PCNSL CSCs might contribute to the tumor vasculature." (PMID 28415725, 2017). "Xenografted cells replicated the phenotype of the original tumour, displaying high expression of nestin, nf-200 and CD133, and no expression of CD15, CD44, GFAP." (PMID 28417956, 2017). "The comparative analysis of immunofluorescence results obtained from particulartumours (G113, G114 and G116) cultured as three experimental models (10%adh, 0% sph, 0% adh) revealed the presence of selected CSCsmarkers (SOX2, nestin and CD44) in G113 and G116 tumour-derived cells." (PMID 28522553, 2017). "We found that cells with tumor morphology co-expressed TfR1 and GFAP; additionally we observed co-expression of TfR1 and the stem cell-related markers CD133 and nestin, which is consistent with recently reported data demonstrating that GBM cells co-express TfR1 and the stem cell-related marker SOX2." (PMID 28837569, 2017). "Nestin staining revealed the presence of neural stem-like progenitor cells throughout the tumor but not within the rest of the brain." (PMID 28358926, 2017). "Qualitatively, Nestin expression seemed to be almost entirely localized to the neoplasm’s margins, while mostly absent from the neoplasm’s center." (PMID 28493990, 2017). "Nestin+ TICs, differentiated Tuj1+ neurons and GFAP+ glial cells were detected in the tumor." (PMID 27549983, 2016).
tumor (continued). "Moreover, we described that neoangiogenesis occurred in the GBM neighbouring tissue, where nestin and CD105 were expressed in microvessels ECs that showed a morphology quite similar to those present in the tumor." (PMID 27705944, 2016). "A single cell from the primary tumor spheres could form secondary tumor spheres, and expressed stem cell makers: CD133, SOX2 or Nestin." (PMID 27557508, 2016). "Endoxifen-induced tumours expressed GFAP, nestin, Sox2, Olig2, PDGFRa and doublecortin (Fig. 5E1-J1), and were indistinguishable from tumours generated by Adeno-Cre or Adeno-GFAP-Cre injection and as shown in Fig. 5E2-J3." (PMID 26704996, 2016). "Importantly, the tumours recapitulated the histopathology and gene expression signatures of human GBM, including presence of necrosis, neovascularization, nestin and Sox2 expression and a strong enrichment in the Verhaak mesenchymal subtype gene signature." (PMID 27350048, 2016). "Altogether, we observed that chemoresistance existed in HCC cells with EMT, thereby enhancing tumor invasion and metastasis; this may provide an explanation for the poor prognostic outcomes in chemo-treated HCC patients with Nestin-overexpressed tumors." (PMID 27412382, 2016). "Here, we analyzed the expression of putative CSC markers—CD24, CD44, epithelial cell adhesion molecule (EpCAM), CD133, and nestin—by immunofluorescence, flow cytometry and quantitative PCR in 3 PDAC-derived cell lines and by immunohistochemistry in 3 corresponding tumor samples." (PMID 27414409, 2016). "Both PDX subsets expressed additional stem cell markers (CD146/CD29/OCT4/NANOG/Nestin) but still contained non-CSC tumor cells." (PMID 26551931, 2016). "Pharmacological blockade of A3AR generated a chemosensitizing effect, enhancing the effectiveness of the MRP1 transporter substrate, vincristine, reducing tumour size and the levels of CD44 and Nestin stem cell markers as well as the Ki-67 proliferation indicator." (PMID 27634913, 2016). "We determined the expression levels of Nestin protien in HCC tumor and adjacent non-tumor tissue IHC." (PMID 27412382, 2016). "VW-MPSC specific expression of Nestin (a type VI intermediate filament protein) was recently identified to demonstrate the MSC origin of mural pericytes and SMCs in vascular stabilization processes during tumor progression." (PMID 26880936, 2016). "In particular, we observed that SAHA treatment could significantly reduce the percentages of tumor cells with positive staining of THBS1, Nestin, N-cadherin, SNAIL/SLUG, Vimentin and b-catenin." (PMID 27634890, 2016). "Moreover, these GSC populations in vitro expressed high levels of “classical” stem cells markers (Nestin, Sox2 and CD133) and low levels of differentiation markers (βIII-tubulin and glial fibrillary acid protein) when compared to bulk tumor cells." (PMID 25955030, 2015). "In C6 glioma cells it was demonstrated that a small fraction of cells that could form tumor spheres also expressed potential stem cell markers CD133 and NESTIN." (PMID 26649310, 2015). "However, activation of CDK5 in cancer induces nestin reorganization, and inhibition of CDK5 reduces tumor growth and metastasis." (PMID 25371063, 2015). "Nestin was expressed in 88.7% (63/71) cases, with almost no expression in alveolar and bronchial epithelial cells in tumor adjacent tissues." (PMID 24498263, 2014). "Interestingly, these tumor spheres recapitulate neurospheres in their expression of stem cell markers such as CD133, Nestin, Oct-4 and CD15." (PMID 25356871, 2014). "Finally, nestin, NSE and GFAP were used as immunohistochemical markers to compare the degree of tumour differentiation between female and male xenotransplanted mice." (PMID 25000562, 2014). "In addition, clinical tumor specimens of patients BC007, BC107, BC515 and BC877 were also found to express nestin (approximately 20 to 80%), βIII-tublin (approximately <10 to 35%) and approximately GFAP (35 to 80%)." (PMID 24670249, 2014).
tumor (continued). "In tumor spheres, TLX is coexpressed with the neural progenitor markers Nestin, CD133 and Oct-4." (PMID 25356871, 2014). "Consistent with the relationship between elevated nestin expression and Ki-67 or PCNA expression in NSCLC tumor specimens, nestin knockdown in tumor cells resulted in a significant decrease in the number of Ki-67-positive cells compared to control tumor cells." (PMID 24498263, 2014). "Tumor cells in control mice were positive for Nestin expression, but no signal was detected in mice injected with CPEB1-overexpressing GSCs." (PMID 25216517, 2014). "The tumor subspheres expressed GFAP, CD133, Nestin, Nanog, CD44, and CD90." (PMID 24432012, 2014). "Frequently, Nestin is not expressed by the cancer cells themselves but can be observed in the endothelial cells of the tumor regardless of malignancy grade or its histotype." (PMID 25364727, 2014). "In contrast, we did not detect any single Nestin(+) endothelial cell, neither in the murine models nor in different human (tumor) specimen investigated here." (PMID 25019063, 2014). "Nestin expression was detected in myoepithelial cells in all of the matched adjacent nontumor areas and in the cytoplasm of tumor cells in 41 specimens (27.33%), consistent with our previous observations." (PMID 25056574, 2014). "Nestin, CD44, and CD133 antigens, markers of stem cell properties, were overexpressed in the neoplasm and could suggest a tumor origin by pluripotent stem cells." (PMID 24959179, 2014). "Intense staining of the vasculature was also seen in the human tumor, but no other nestin positive cells, not even the tumor cells themselves, were observed within the tumor bed." (PMID 23527265, 2013). "The majority of GBM cells in non-irr tumor reflected their stem cell characteristics by a strong Nestin signal and a low GFAP presence." (PMID 24052948, 2013). "RT-qPCR analysis on elderly HCCs demonstrated that the high expression levels of 7 putative hepatic stem/progenitor cell biomarkers (including keratin 19 (K19), ABCG2, CD44, Nestin, CD133, EPCAM and OV6), is related to tumor angiogenesis and a poor prognosis for the HCC." (PMID 24160375, 2013). "In the xenograft, we observed nestin positive mouse neural stem cells in the ventricles, where expected, but no positively stained cells were found within the tumor bed except for the vasculature." (PMID 23527265, 2013). "Among p16INK4a-positive tumours, CAF-1/p60, PARP-1 and nestin were only barely detectable." (PMID 22882088, 2012). "Mouse nestin also stained blood vessels in the cerebellum of tumor-bearing mice, although no tumor mass was apparent in the cerebellum." (PMID 22539956, 2012). "The invasive edge, as well as the tumor periphery, was populated by SDF-1-expressing cells with elongated morphology and several terminal processes, reminiscent of invasive neural progenitors that were stained by host nestin." (PMID 22539956, 2012). "Nestin protein and mRNA were diffusely localized in cancer cell nests in the nonkeratinizing and keratinizing tumor cells." (PMID 22580387, 2012). "The cell of origin of ependymomas may be the radial glia cells as tumor-derived spheres displayed an immunophenotype (CD133+, nestin+, radial glia marker RC2+, and brain-lipid binding protein (BLBP+)) similar to that of normal radial glia cells." (PMID 21394230, 2011). "In order to estimate whether these tumor spheres showed NSC properties, we stained the tumor spheres from patients with anti-Nestin antibody." (PMID 21342503, 2011). "Tumor spheroids retained expression of the classical neural stem cell markers CD133 and nestin." (PMID 18985161, 2008). "Moreover, these ρ0 cells display the ability to form “tumor spheroids” in serumless medium and are positive for CD133 and the neural progenitor cell marker, nestin." (PMID 18985161, 2008).